PHOX2B (paired like homeobox 2B)
Diseases named in the same sentence as PHOX2B in open-access papers (continued):
Sharing a sentence is not in itself a finding about the gene and the disease.
tumor (70 papers, 2009 to 2025). "Studies of familial cases of NB allowed for identification of two NB susceptibility genes (ALK, PHOX2B) yet their mutations are present in about 10% of sporadic tumours." (PMID 20003389, 2009). "MYCN amplification, activating mutations in the ALK receptor tyrosine kinase, TERT rearrangements, inactivating ATRX mutations and dominant negative mutations in PHOX2B are among the most recurrent genetic events that drive oncogenic signaling and tumor formation." (PMID 30952905, 2019). "PHOX2B mutations may trigger a wide range of autonomic nervous system disorders, ranging from congenital malformation to tumour predisposition." (PMID 25928806, 2014). "The PHOX2B wild type may therefore act as a tumour suppressor gene which is de-repressed by PHOX2B mutations in the homeodomain." (PMID 25928806, 2014). "In particular, three kinds of PHOX2B genetic elements seem to play a role in NB occurrence: missense (MS) mutations, frameshift (FS) mutations and unbalanced gene expression found in both sporadic and familiar cases of isolated NB and in both isolated and syndromic forms of the tumor." (PMID 34771690, 2021). "miR-204 is particularly pivotal, where it acts as a tumour suppressor in NB by directly targeting both PHOX2B and MYCN." (PMID 40779030, 2025). "Our findings confirm previous observations that PHOX2B sensitivity is most evident in samples with low tumor infiltration, such as bone marrow samples during treatment." (PMID 40753395, 2025). "Primary tumor cells were isolated, cultured, and characterized using Phox2b and synaptophysin staining." (PMID 40552293, 2025). "MiR-204 is known as a tumor suppressor that targets multiple oncogenes, including MYCN, BCL2, NTRK2 and PHOX2B, which are associated with tumor progression and chemoresistance in NB." (PMID 39594898, 2024). "Metastatic tumor cells clustered with adrenergic cells and showed high expression of adrenergic signature genes PHOX2B, MDK, and KCNQ2." (PMID 38358826, 2024). "Tumor cells were characterized by high expression of NB tumor signature genes (PHOX2B, HAND2, STMN2, and KCNQ2), which were exclusively expressed in the BM of metastatic patients with NB." (PMID 38358826, 2024). "Upon performing immunohistochemistry (IHC) on the tumours obtained from xenografting, it was revealed that PHOX2B was expressed in the majority of these tumours, even those originating from mesenchymal cell populations." (PMID 37887559, 2023). "Unexpectedly, as revealed by IHC analysis, PHOX2B expression was observed in most tumor cells from the whole set of xenografts, even those obtained after engraftment of mesenchymal populations." (PMID 37142597, 2023). "The upregulation of HDAC2 and PHOX2B accelerated tumorigenesis and enhanced tumor volume after 28 days." (PMID 35060363, 2022). "The integration of the 10 biopsies (n=20,296 cells) highlighted tumor cells (PHOX2B+, GATA3+) as well as several populations of the TME." (PMID 36054452, 2022). "Sanger sequencing of ALK and PHOX2B, SNP microarray of three tumor samples and whole genome sequencing of tumor and blood were performed." (PMID 36140661, 2022). "Two tumor samples, T14 and T19, displayed a loss of 4p13 that encodes RHOH, a member of the RAS superfamily, and PHOX2B, a homeobox transcription factor." (PMID 34285259, 2021). "Experiments with spiking ratios of 1:1000 and 1:10,000 (PDX-1 cells to PBPCs) were performed, subsequently using RT-PCR to quantify tumor cells by measuring expression of PHOX2B, TH, and DDC." (PMID 34654486, 2021). "RT-PCR was chosen as analysis method to quantify minute numbers of tumor cells by measuring expression of PHOX2B, TH, and DDC." (PMID 34654486, 2021). "In the future, we will analyze the relationship between the NB5 assay and prognosis and explore the relationship between tumor relapse and PHOX2B, TH, DDC, CHGA, and DCX expression." (PMID 34055604, 2021).
tumor (continued). "These cells were proposed to “represent a population of malignant sympathetic neural crest or early progenitor cells that give rise to Phox2b positive tumor cells comprising the bulk of NB tumors”." (PMID 24947326, 2014). "PHOX2B is also reported to be directly suppressed by additional tumour suppressive miRNAs." (PMID 40779030, 2025). "In the metastasis-associated neoplastic cell states, we detected robust expression of neural crest (ZIC1, OLIG3), mesenchymal (MSX2, GDF6), and metastasis-related (DKK2) genes in addition to adrenergic genes (e.g., PHOX2B) that were shared with primary tumor cell states." (PMID 41279557, 2025). "PLK4 expression in the tumor tissues markedly varied with the degree of differentiation, and it was notably elevated in poor-differentiated regions compared with well-differentiated regions, wherein the expression of PHOX2B, CXCR4, and cyclin D1 was higher." (PMID 40860200, 2025). "Whole exome sequencing results revealed that such EV-DNA carried tumor-specific genetic mutations, including those occurring on known oncogenes and tumor suppressor genes in neuroblastoma (ALK, CHD5, SHANK2, PHOX2B, TERT, FGFR1, and BRAF), and represented the entire exome." (PMID 39402599, 2024). "Based on recent studies and extrapolating the regulation patterns from other tumor entities, hereby we have intended to depict a structural and functional model in which Nrf2, NF-κB and Phox2B may compose a transcription factor network." (PMID 38666930, 2024). "In total, eight cell types could be defined in addition to tumor cells represented by several clusters and defined by the expression of the Phox2b transcription factor." (PMID 36054452, 2022). "It revealed that upregulation of HDAC2 and PHOX2B promoted tumor weight." (PMID 35060363, 2022). "Determination of whether there is any connection between PLAGL2 amplification in this CNS embryonal tumor and expression of PHOX2B will require closer study." (PMID 35763016, 2022). "Paired-like homeobox 2b (PHOX2B) is one of the most sensitive and specific tumor-related biomarkers, which could be detected by RT-qPCR to evaluate minimal metastatic or residual lesions of NB." (PMID 35082556, 2022). "Finally, TBX2 expression is positively correlated with GATA3, HAND2, and PHOX2B expression levels as well as with those of other potential CRC genes important in development in a NB tumor cohort (n = 283)." (PMID 30451831, 2018). "Furthermore, Lig3, Lig1 and PARP1 silencing also significantly blocked protein expression of neuronal developmental and NBL tumor markers (TH, Phox2b, TRKB) in differentiating NCSC-MYCN cells, quantified by Western blot analysis." (PMID 29238067, 2017). "Like PHOX2A, PHOX2B, is overexpressed in a number of tumours and NB cell lines." (PMID 26902400, 2016). "There was a discrepancy between the in vivo results indicating that the knockdown of PHOX2B promoted local tumor formation and increased metastatic load, and the in vitro results demonstrating that PHOX2B knockdown did not affect proliferation and decreased the migratory capacity of the cells." (PMID 26840262, 2016). "Elevated TET3 expression is correlated with improved 5-year survival (42%), and the tumor-suppressive role of TET3 is mechanistically linked to the 5mC hydroxylation-mediated maintenance of open chromatin states at neurodifferentiation-associated genes (e.g., PHOX2B)." (PMID 40787450, 2025). "The underlying mechanism or genetic correlate for focal PHOX2B expression observed in the five positive ETMR cases and in the PLAGL2‐amplified case is not entirely clear but may correspond to neuronal differentiation among tumor cells." (PMID 35763016, 2022).
tumor (continued). "We assessed PLK4, PHOX2B, CXCR4, and cyclin D1 expression by IHC in tumor tissues from the same patients exhibiting variable differentiation status." (PMID 40860200, 2025). "Tumors displayed an undifferentiated morphology, were positive for the NB marker PHOX2B, and maintained high amounts of MES markers SOX9 and LGR5 along with low ADR marker TH, in concordance with the parental relapse tumor." (PMID 36306349, 2022). "In line with tumor growth, orthotopic tumors also showed higher expression of GAB2, PHOX2B genes than the subcutaneous tumor." (PMID 35197367, 2022). "From the CRC network, only ASCL1 emerged from this analysis, given its different dynamic expression during murine TH-MYCN-driven tumor formation compared to HAND2, PHOX2B, GATA3 and ISL1." (PMID 34638267, 2021). "PHOX2B immunohistochemical staining was performed on some xenografts, and with one exception (CCI-NB06-RMC, from A6580) showed nuclear positivity in tumour cells." (PMID 31919402, 2020). "Through various prioritization strategies, we provide a core set of lincRNAs with a potential role in NB tumor biology, up- or downstream of the key NB driver genes MYCN, ALK and PHOX2B." (PMID 30952905, 2019). "Therefore, i) PHOX2B and ALK mutations are involved either in the initiation or the progression of NB and ii) wild-type as well as mutated transcripts of both these genes are reported to be overexpressed in the vast majority of the NB cell lines and tumor samples analyzed." (PMID 20957039, 2010). "Remarkably, Hand2, Phox2b, Gata3 and Isl1 were highly expressed in both TH-MYCN+/+ early hyperplasia and wild-type ganglia at week 1 and remained at this level in both tissues throughout further tumor development." (PMID 34638267, 2021). "In this review, we have focused on the circuitry linking the oncogenic transcription factors MYCN and PHOX2B with their transcriptional targets ALK and LIN28B and the tumor suppressor microRNAs let-7, miR-34 and miR-204, which should act as down-regulators of their expression." (PMID 34771690, 2021). "Most of the tumor cells expressed Phox2b, and the majority of the Phox2b+ tumor cells expressed Ki67, but no measurable levels of Th." (PMID 33585251, 2020). "Retrospective staining of the A6580 donor tumour, an intracranial metastasis, confirmed the absence of PHOX2B staining." (PMID 31919402, 2020). "We anticipate that a panel of markers, such as BPTF, TMCO3, CUX2, combined with classic markers: PHOX2B, TH, DCX, will prove valuable in a variety of clinical settings, including the assessment of tumor, drug resistance, residual disease monitoring and prediction of recurrence." (PMID 29467591, 2018). "Our GD2 positive cell preparations were enriched in CD56+ and NB84+ mononuclear NB cells, showed the same genetic aberration as the primary tumor cells, and expressed NB-specific genes, such as TH, GD2 synthase, Phox2b, ELAV4 and DCX, at the same levels as primary tumor cells." (PMID 22253825, 2012). "Immunohistochemical analysis demonstrated that CD56 and neuron-specific enolase (NSE) were positive in tumor cells, while CD199, S-100 and PHOX2B were negative, and staining for the proliferation marker Ki-67 showed 60% positive cells." (PMID 31804335, 2019). "By immunohistochemistry, the tumor cells expressed synaptophysin, chromogranin, NKX2.2 (diffuse, nuclear), GFAP (patchy), SMI31 (neurofilament) (focal, cytoplasmic), and TdT (diffuse, nuclear), while lacking expression of CD99, TTF-1, CK20, MCPyV, PHOX2B, Olig2, OCT3/4, CD45, CD3 and PAX5." (PMID 38031161, 2023).
cancer (17 papers, 2011 to 2026). A tumor composed of atypical neoplastic, often pleomorphic cells that invade other tissues. "The first two of these compounds (17AAG and curcumin) have been extensively studied for their anti-cancer benefits, and are of interest for our system since Phox2B variants are also associated with an increased incidence of neuro- and medulloblastoma." (PMID 29588456, 2018). "Profiling the resulting enriched samples with immunohistochemistry and mRNA expression of 1490 cancer-related genes via NanoString, 13 of 17 samples contained CTCs displaying cytologic atypia, TH and PHOX2B expression and/or upregulation of cancer-associated genes." (PMID 36176417, 2022). "At this point, MYCN, ALK, RET and Phox2B built a complex network involved in different types of cancer, mostly involving the nervous system, also in regard to NF-κB (RelA/p65)." (PMID 38666930, 2024). "When expanding our investigation of other cancer predisposition genes besides ALK and PHOX2B, we detect rare variants such as a nonsense mutation in BARD1 as well as missense variants in CHEK2, BRCA2, and WRN." (PMID 33384420, 2020). "Although genes like WT1, GATA3 and PHOX2B were frequently hypermethylated in several cancer types, others were restricted to certain tissue types." (PMID 28581523, 2017). "Upon mapping the list of peptides to genes and referencing those genes for tissue expression levels, we observed several known cancer targets with favorable therapeutic windows, including PHOX2B, PRAME, and SOX11, a primarily developmental transcription factor expressed in many different tumors." (PMID 41477871, 2026). "When grouped by ZNF536 expression, we found that in the cancer epithelium, ZNF536 exhibited co-expression with PHOX2B and AR, while being excluded from IFI27, IFI6, and ZFP36." (PMID 38720348, 2024). "In normal development rather than in the aberrant genetic circuits set up in cancer, PHOX2B works with other developmental transcription factors to drive noradrenergic neuron differentiation." (PMID 36263020, 2022).
genetic disease (6 papers, 2017 to 2025). "CCHS (OMIM #209880) represents a rare human genetic disorder of the Autonomic Nervous System (ANS) caused by heterozygous mutations in PHOX2B." (PMID 32654284, 2021). "The purpose of this study was to describe the sleep structure (especially slow wave sleep) in adults with congenital central hypoventilation syndrome (CCHS), a rare genetic disease due to mutations in the PHOX2B gene." (PMID 28115003, 2017). "Congenital central hypoventilation syndrome (CCHS) is a rare genetic disease caused by mutations of the PHOX2B gene." (PMID 28115003, 2017). "Heterozygote polyalanine expansion mutations in the exon 3 of PHOX2B are responsible for the majority of cases of CCHS, a rare genetic disease that affect the autonomic nervous system and central CO2 chemoreflexes." (PMID 38727716, 2024).
infection (6 papers, 2016 to 2026). The state of being infected such as from the introduction of a foreign agent such as serum, vaccine, antigenic substance or organism. "In four patients with recurrent apnea, infection, hypoxemia, and pathogenic variants, PHOX2B was identified." (PMID 34733806, 2021). "Four weeks after shRNA infection, we observed a further reduction in the expression of PHOX2B in Nmb neurons and a significant reduction of the CO2 chemoreflex, while ventilation in normoxia or hypoxia was unaffected." (PMID 38727716, 2024). "qRT-PCR assays showed that following infection with PHOX2B-specific shRNA, PHOX2B mRNA expression decreased almost four fold (p<0.05) in the MicroNB-shPHOX2B cells." (PMID 26840262, 2016). "Importantly, we also observed a reduction in PHOX2B+ neuron numbers across 10 days of EV infection for all tested EVs, and this decrease in motor neurons was much more rapid upon PV infection." (PMID 41332624, 2025).
neurodevelopmental disorder (4 papers, 2016 to 2026). A behavioral and cognitive disorder with onset during the developmental period that involves impaired or aberrant development of intellectual, motor, or social functions. "CCHS is a neurodevelopmental disorders due to heterozygous polyalanine expansion mutation (PARM) in the PHOX2B gene, a transcription factor involved in the development of the autonomic nervous system (ANS), including the neuronal structures that control breathing and integrate respiratory reflexes." (PMID 33510615, 2020). "Heterozygous mutations of the human PHOX2B gene, a key regulator of autonomic nervous system development, lead to congenital central hypoventilation syndrome (CCHS), a neurodevelopmental disorder characterized by a failure in the autonomic control of breathing." (PMID 27129232, 2016).
neurological disorder (2 papers, 2022 to 2024). "Heterozygous mutations of the transcription factor PHOX2B are responsible for Congenital Central Hypoventilation Syndrome, a neurological disorder characterized by inadequate respiratory response to hypercapnia and life-threatening hypoventilation during sleep." (PMID 35563209, 2022). "Heterozygous mutations in the PHOX2B coding region are responsible for the occurrence of Congenital Central Hypoventilation Syndrome (CCHS), a rare neurological disorder characterised by inadequate chemosensitivity and life-threatening sleep-related hypoventilation." (PMID 38727716, 2024).
respiratory disorder (2 papers, 2021 to 2022). "More recently, the characterization of a CCHS disease-causing frameshift mutation in LBX1 has further revealed that this respiratory disorder originates from the misspecification of dB2 neurons in mice, and that this is caused by a lack of cooperativity between PHOX2B and LBX1." (PMID 36523603, 2022).
autosomal dominant disease (1 paper, 2016). Autosomal dominant form of disease. "This is a rare genetic, autosomal dominant disease, caused by mutation in PHOX2B gene, located in chromosome band 4p12, which results in autonomic nervous system dysfunction." (PMID 26838603, 2016).
CNS tumors (1 paper, 2022). "In this study, we investigated the utility of PHOX2B immunohistochemistry in a variety of CNS tumors with embryonal morphology." (PMID 35763016, 2022). "However, only limited studies have evaluated the pattern and extent of PHOX2B immunoreactivity in CNS tumors." (PMID 35763016, 2022). "Care should be taken in interpreting PHOX2B immunopositivity in a differential diagnosis that includes metastatic neuroblastoma and CNS tumors; focal or patchy expression should not be considered definitively diagnostic of metastatic peripheral neuroblastoma." (PMID 35763016, 2022). "Focal or patchy nuclear staining with PHOX2B is not specific and can be observed in primary CNS tumors, particularly ETMR." (PMID 35763016, 2022).
PHOX2B also shares sentences with these, for which no sentence is quoted: alveolar rhabdomyosarcoma (2 papers); Anisocoria (2); breast carcinoma (2); Ewing sarcoma (2); ganglioneuroma (2); neuroblastic tumor (2); Strabismus (2); acute lymphoblastic leukemia (1); adrenal tumors (1); alcohol use disorders (1); Alzheimer disease (1); Anorexia (1); bipolar disorder (1); cardiac arrhythmia (1); central sleep apnea (1); childhood cancer (1); chondrosarcoma (1); cleft palate (1); cleidocranial dysplasia (1); cocaine use disorder (1); cognitive deficits (1); congenital heart disease (1); cryptorchidism (1); depression (1); fibroma (1); Haddad syndrome (1); Hearing impairment (1); heart failure (1); hyperprolactinemia (1); Hypertension (1).
A further 28 diseases each share a sentence with PHOX2B in 1 paper.